EGFR (epidermal growth factor receptor)
Diseases named in the same sentence as EGFR in open-access papers (continued):
Sharing a sentence is not in itself a finding about the gene and the disease.
tumor (continued). "Also, upregulation of VEGF and interleukin-8 (IL-8) connoted tumor cell angiogenesis, while EGFR, STAT-3, PI3K, and NOTCH upregulation influenced signal transduction pathways." (PMID 34490084, 2021). "MiR-107 is a tumor suppressor that targets the epidermal growth factor receptor (EGFR)." (PMID 34635059, 2021). "Thus, the binding affinity and kinetics of EGFR-specific repebodies positively correlated with the in vitro tumor-targeting activity." (PMID 33615202, 2021). "Furthermore, in H1975 (EGFR L858R/T790M) mutant cells and A549 (K-Ras G12S) xenografts developed in nude mice after treatment with GO-203, tumor regressions were observed." (PMID 34976811, 2021). "The Ding team embedded platinum-based drug 56MESS into a double-stranded DNA tetrahedron by the intercalation method, and coupled with a nano antibody targeting the inhibition of epidermal growth factor receptor (EGFR, one of tumor markers), in order to implement multi-drug combination therapy." (PMID 34944499, 2021). "In the present study, GPER was downregulated in HCC tissue compared with that in matched non-tumor counterparts, and GPER-specific agonist G1-triggered GPER/EGFR/ERK signaling played a crucial role in decreasing the tumor viability of HCC, both in vitro and in vivo." (PMID 33767999, 2021). "Since HER2 and EGFR are well-known heterodimerization partners, the fact that both are found to be highly co-activated in the pre-treatment tumor samples of responding patient population provide further evidence of functional HER2-driven pathway activation and signaling coherence." (PMID 34741023, 2021). "Elucidating the molecular events that affect EGFR trafficking during tumour progression may contribute to understanding the mechanisms regulating tumour progression and to improving CTX efficacy by overcoming primary resistance." (PMID 35008337, 2021). "Therefore, the use of CT features for patients can allow analyses of tumours and more accurately predict patient populations who will benefit from EGFR-TKIs or ALK crizotinib treatment." (PMID 33707479, 2021). "Interestingly, this study also showed that resistance to RAF1 or EGFR ablation separates two different groups of PDAC tumours at the molecular level." (PMID 33920182, 2021). "However, the clinical efficacy of EGFR inhibitors still remains limited due to development of tumour resistance; hence, most tumours eventually relapse." (PMID 35052732, 2021). "In brief, EGFR signalling is correlated with tumor proliferation, invasion, and metastasis." (PMID 34578147, 2021). "However, EGFR T790M has also been documented on pretreatment tumor samples in a subgroup of patients, thus suggesting the existence of sub-clones before the beginning of treatment." (PMID 33922215, 2021). "In addition, relapsed tumor tissues from EGFR‐mutant NSCLC patients after first‐line treatment with osimertinib are required." (PMID 33764690, 2021). "explored several HNSCC cell lines and found that the programmed death ligand-1 (PD-L1), which limits the function of activated T lymphocytes when they interact with the ICP receptor programmed death-1 (PD-1), is expressed by tumor cells in an EGFR- and JAK2/STAT1-dependent manner." (PMID 33718169, 2021). "However, this will require standardisation of criteria, particularly for copy numbers of the EGFR gene and the proportion of tumor cells demonstrating EGFR amplification as has been achieved for HER2 in breast and gastric cancer." (PMID 34912708, 2021). "The mouse tumor experiment employed colon or breast tumors with high levels of EGFR expression." (PMID 33738260, 2021). "EGFR signaling pathway plays an important role in physiological processes such as cell growth, proliferation and differentiation, and is closely related to cancer cell proliferation, angiogenesis, tumor invasion, metastasis, apoptosis and prognosis." (PMID 33792624, 2021).
tumor (continued). "This suggests that the use of an EGFR inhibitor could reduce, or negate, the benefit of platinum-based cytotoxic chemotherapy in patients with EGFR-driven tumours and would thus be antagonistic." (PMID 33169187, 2021). "Concentration-dependent reductions in both cell viability and tumor uptake were observed when this model was treated with Erlotinib, a molecular agent targeting the tyrosine-kinase domain of the EGFR, which further reinforces the nanobody’s promisingly high affinity and receptor specificity." (PMID 33925941, 2021). "However, removal of EGF ligand or addition of EGFR inhibitor led to a significant reduction in growth of tumour organoids when combined with RAC1B knockdown." (PMID 33879799, 2021). "In order to test whether changes in the levels of total EGFR occurred during tumor sphere formation and serial passages, whole cell lysates of parental cells and tumor spheres at passage 1–3 were analyzed by western blot." (PMID 33922104, 2021). "Despite the observation that adding panitumumab to EOX had a negative prognostic role in both groups, it was unexpected to notice that the negative association between EGFRi and EOX appeared more pronounced in patients whose tumour harboured an EGFR amplification." (PMID 33199443, 2021). "In oncogene addicted cells activation of RTK bypass signaling triggered by EGFR (or other RTK) inhibition could promote survival of subsets of tumor cells that lead eventually to secondary resistance." (PMID 34853306, 2021). "While tissue biopsy is still irreplaceable in diagnosing tumor malignancy, we intend to investigate whether liquid biopsy could be conducted to detect EGFR-TKI resistance mechanisms in NSCLC patients and hopefully save patients from undue suffering." (PMID 33718183, 2021). "WW domain-binding protein 2 (WBP2) is an emerging oncoprotein profoundly implicated in a variety of transduction systems, such as Wnt, Hippo, epidermal growth factor receptor (EGFR) and steroid signaling pathways, and human cancers including breast malignancies." (PMID 34117091, 2021). "In an animal study using EGFR mutated tumor-bearing mouse model, osimertinib (but not gefitinib) combined with anti-PD-L1 therapy was shown to cause pneumonitis and injury to lung tissues." (PMID 34113560, 2021). "In the tumor cell, EGFR such as transferrin and folate are usually overexpressed." (PMID 33525729, 2021). "The in vivo and in vitro results all demonstrated that EGFR-targeted nanosystems could effectively ablate tumor tissue by synergistic treatment of chemotherapy and photothermal therapy." (PMID 34322025, 2021). "Co-administration of tofacitinib with the immunotoxin LMB-100 or the anti-epidermal growth factor receptor (EGFR) mAb BV421 increased the number of tumor cells with LMB-100 uptake by 48% and the number of tumor cells with BV421 uptake by 133%, 3 h after administration." (PMID 35979855, 2021). "Capsaicin inhibited the EGFR-induced invasion and migration of human tumor cells." (PMID 34836251, 2021). "Given the significant level of amino acid sequence identity (>95%), the group of EGFR-specific repebodies can be considered as an ideal starting point to clarify whether tumor localization of binding proteins is proportional to their target-binding affinities." (PMID 33615202, 2021). "In addition, GR-positive non-tumor liver tissues featured lower EGFR expression and higher ERRFI1 mRNA expression than GR-negative tissues." (PMID 33806040, 2021).
tumor (continued). "In the current study, the results of the cytokine array study revealed that the plasma EGF level was higher in the young age group than in the old age of patients with NPC with local recurrence or metastasis; in addition, tumor EGFR expression was higher in the young age group." (PMID 34204797, 2021). "As a novel CT response, the presence of cavitation and attenuation changes within a target lesion can be used for response evaluation in patients with NSCLC who have undergone EGFR-TKI therapy, as cavitation within a tumor is caused by hampered angiogenesis and subsequent tumor necrosis." (PMID 33592873, 2021). "IHC data indicated that 60.6% of the tumors had a basal-like phenotype (i.e., a TNBC tumor that expresses at least one of the two basal markers, EGFR and CK5/6) and 36.5% of the tumors had a molecular apocrine phenotype (i.e., a TNBC tumor that expresses both AR and FOXA1)." (PMID 33673133, 2021). "T790M deletion may be the result of third-generation EGFR-TKI treatment and may also be one of the causes of drug resistance, which is related to the heterogeneity of tumors in the process of tumor progression." (PMID 34575576, 2021). "Thus, downregulation of the EGFR-axis by targeted therapies or via traits of the tumor microenvironment can prevent PD-L1 upregulation in tumor cells and enhance their immunogenicity." (PMID 33718186, 2021). "One of the theories stated that the role and dominance of EGFR signaling may change during tumor progression." (PMID 34638492, 2021). "To extend, GPR87 trans-activated EGFR to promote scattering and extension of tumour cells." (PMID 34809653, 2021). "ABT-806 is a humanized, tumor-specific anti-EGFR IgG1 monoclonal antibody." (PMID 34207383, 2021). "Moreover, we also found that depletion of TUC338 led to the inactivation of EGFR/PI3K/AKT pathway in vivo by using the xenograft tumor model." (PMID 33986803, 2021). "Among the EGFR-TKI resistance signaling pathways, KRAS is an important signaling pathway downstream of EGFR, and the mutated KRAS gene directly activates the MAPK signaling pathway without relying on the activation of upstream EGFR, leading to tumor proliferation and metastasis." (PMID 34178945, 2021). "Whether EGFR would be the target of imipramine for suppressing tumor signaling transduction and results in anti-tumor potential is remaining unclear." (PMID 34765548, 2021). "The present study was conducted to affirm our hypothesis that tumor hypoxia negatively modulates EGFR protein abundance and activity which might alter the tumor response upon combined modality treatments." (PMID 33718186, 2021). "Similarly, tumor tissues retrieved from ALOC-EO treated mice showed impaired EGFR phosphorylation mice indicating that ALOC-EO suppresses EGFR signaling." (PMID 34360915, 2021). "Evidence shows that EGFR-mutation drives a low immunogenic tumor microenvironment characterized by a lack of TILs and a low mutation burden." (PMID 33430239, 2021). "In summary, when disease control is the treatment goal, most experts suggest that the primary tumor location should be considered, and anti-EGFR shows better treatment outcomes in left-sided RAS/BRAF WT mCRC because1L treatment is based on current clinical evidence." (PMID 34868987, 2021). "Similarly, in the early stage of tumorigenesis, tumor suppressive autophagy inhibits the excessive proliferation and malignant transformation of ISCs by degrading epidermal growth factor receptor (EGFR)." (PMID 34414192, 2021). "The dynamic plasma cfDNA level may be helpful for monitoring tumor response, predicting patient outcomes, and identifying resistance mechanisms during the third-generation EGFR TKI treatment in clinical practice." (PMID 33842353, 2021).
tumor (continued). "Inhibiting EGFR pathway using an anti-EGFR antibody, cetuximab, inhibits tumor growth." (PMID 34298758, 2021). "Our hypothesis is that integrating these radiomic phenotypes with ctDNA and clinical variables can improve assessment of tumor heterogeneity and outcome prediction to EGFR-targeted therapy for metastatic NSCLC." (PMID 33976268, 2021). "Moreover, tumor biopsy samples from EGFR-TKI resistance patients presented increased vimentin expression and downregulated E-cadherin expression compared with tumor tissues taken before TKI treatment." (PMID 33170304, 2021). "In another Phase III trial (OAK) evaluating atezolizumab (an anti-PD-L1 monoclonal antibody), NSCLC patients with EGFR-mutated tumor also did not achieve OS benefit from the immunotherapy over docetaxel." (PMID 34113560, 2021). "Furthermore, its impairment in EGFR-MT tumor results in an unfavorable response to anti-PD-1 immunotherapy." (PMID 34663810, 2021). "And the activation of the EGFR signal pathway contributes to the development of EMT in tumor cells." (PMID 34819077, 2021). "However, overexpression of EGFR engenders constitutive activation of the EGFR and has been shown to correlate with tumor proliferation, tumor metastasis, and resistance to chemotherapy." (PMID 33898431, 2021). "Our data indicating that the combination of gefitinib with cisplatin is antagonistic (in TE8 and OE21 cells) are at odds with reports that treatment of TE8 xenograft tumours with cisplatin in combination with EGFR inhibition by cetuximab significantly reduces their size." (PMID 33169187, 2021). "Furthermore, overexpression of EGFR (or HER2/ERRB2) is not characteristic for the majority of tumour samples obtained from HNSCC patients, and EGFR downstream activity in tumour tissues is significantly below the levels observed in HNSCC cell lines." (PMID 34944837, 2021). "Furthermore, OPB proved effective in patients with TKI-resistant EGFR mutation NSCLC, by reducing tumor burden significantly." (PMID 34777681, 2021). "Immune checkpoint inhibitor therapies showed durable improvements in outcomes of HNSCC patients, but as for EGFR-targeted therapies, response rates are very low and tumor cells frequently acquire immunosuppressive resistance to the cytotoxic activity of immune effectors." (PMID 33718186, 2021). "Although controversial, false negative results for EGFR mutations can also result from tumor heterogeneity." (PMID 34440926, 2021). "This method is reliable and clinically relevant, enabling the detection of tumor-specific mutations in CSF that direct therapy (e.g., EGFR, BRAF) even in patients with no measurable systemic disease." (PMID 34625644, 2021). "Additionally, Au component was used as positron emission tomography (PET) probe for imaging of EGFR positive tumor cells." (PMID 34322025, 2021). "EGFR is a carcinogenic tyrosine kinase that promotes the proliferation, differentiation, metastasis and angiogenesis of tumor cells and directly regulates tumor cell autophagy." (PMID 34046198, 2021). "Moreover, activation of the EGFR pathway increases the production of VEGF-A in tumor cells which interacts with VEGFR2 on endothelial cells and promotes the proliferation, migration and differentiation of endothelial cells in a paracrine manner." (PMID 33804477, 2021). "When EGFR is activated, caveolin-1, which inhibits anoikis and promotes tumor metastasis, is also activated, and Src, a signaling transducer, subsequently activates Akt to promote cancer cell and tumor proliferation." (PMID 34094906, 2021). "Furthermore, through functional assays using patient tumor-derived cell lines, we reveal that this EGFR amplification results in increased activity of the EGFR pathway." (PMID 34912708, 2021).
tumor (continued). "Moreover, in mice bearing subcutaneous A431 xenografts, the biodistribution and tumor targeting of 99mTc-labeled anti-EGFR Nbs were investigated by pinhole SPECT/Micro-CT." (PMID 34575943, 2021). "Furthermore, the LncRNA H19 SNP rs217727 and rs2107425, especially the LncRNA H19 SNP rs217727, are correlated to an advanced tumor status for LADC individuals with EGFR wild-type." (PMID 33799753, 2021). "Cetuximab blocks the ligand-binding site of EGFR, preventing signaling and subsequent tumor growth." (PMID 34681717, 2021). "Interestingly, uPAR mediates the shift from tumor cell dormancy to proliferation through an extensive cross talk with epidermal growth factor receptor (EGFR)." (PMID 33535668, 2021). "With ability to bind specifically to EGFR-upregulated cells in tumor tissues, GE11-mediated delivery of therapeutic cargoes proceeds without activating the EGF-receptor, and thus, this method of delivery appears to be appropriate for treating different types of cancers." (PMID 33800282, 2021). "To determine whether inhibition of RAC1B might cooperate with EGFR inhibition to increase the efficacy of treatment in human tumour organoids, we designed a Vivo-Morpholino to target human RAC1 exon 4 (hRAC1B PMO)." (PMID 33879799, 2021). "Drugs targeting EGFR, e.g., afatinib, which irreversibly inhibits HER2, HER4, and EGFR kinases; Erbitux, a chimeric (mouse/human) anti-EGFR monoclonal antibody (mAb); or erlotinib that binds reversibly to the receptor’s ATP binding site, have activity in different tumor types." (PMID 34681618, 2021). "Notably, first-generation EGFR tyrosine kinase inhibitors (TKIs), including gefitinib and erlotinib, significantly reduced the tumor size and improved the overall survival of NSCLC patients with EGFR mutations." (PMID 34068421, 2021). "Furthermore, overexpression of EGFR is correlated with increased tumor size, lymph node involvement, and decreased survival in invasive breast cancers." (PMID 33663560, 2021). "No patients in the enrolled cohort had a known BRAF or EGFR mutation or an ALK rearrangement in their primary tumor." (PMID 34642329, 2021). "IgG4 was less potent in eradicating EGFR-expressing tumor cells by ADCP than IgG1." (PMID 33628623, 2021). "Next, we asked whether LKB1 protein expression in tumor tissues correlates with the clinical outcome of patients with EGFRWT NSCLC who received EGFR TKI treatments." (PMID 33335306, 2021). "Deletion of EGFR suppressed mutant KRAS activity and caused tumor growth temporarily." (PMID 34200786, 2021). "Some evidence suggests that T790M subclonality, i.e. the presence of EGFR T790M-positive cells in only a subset of tumour cells, might influence the response of NSCLC patients to the third-generation TKI osimertinib." (PMID 33741979, 2021). "Combining circulating-tumor DNA (ctDNA), clinical variables, and radiomic phenotypes may improve prediction of EGFR-targeted therapy outcomes for NSCLC." (PMID 33976268, 2021). "However, a previous study showed that ROS stimulated angiogenesis and tumor progression by reducing the expression of CXCL14 via EGFR/MEK/ERK signaling pathway in HNSCC cells." (PMID 34744744, 2021). "Taken together, the data suggest that 14-3-3σ expression in tumor cells might promote survival by regulating EGFR ubiquitination and sustaining EGFR signaling at the cell surface, ultimately enhancing the anoikis resistance of tumor cells." (PMID 33391517, 2021). "Additionally, EGa1-L was shown to inhibit tumor cell proliferation (in vitro) and downregulate EGFR (in vivo)." (PMID 34575943, 2021). "In addition, a clonal evolution study showed an EP300 rearrangement in an EGFR-mutant tumor before transforming to SCLC through EGFR-TKI treatment." (PMID 34121659, 2021). "For example, the minimum levels of activated EGFR may be enough to maintain the growth of some cancers, as has been demonstrated by observing HSC3 cells expressing endogenous levels of EGFR-GFP in mouse tumor xenografts." (PMID 34799560, 2021).